ADORA2A (adenosine A2a receptor)
Description:
Receptor for adenosine (By similarity). The activity of this receptor is mediated by G proteins which activate adenylyl cyclase (By similarity).
Synonyms: ADORA2; RDC8; A2aR
Tractability: Small molecule: an approved drug acts on it; a structure with a bound ligand is known; a high-quality ligand is known; it has a high-quality binding pocket; it belongs to a druggable protein family. Antibody: its Gene Ontology location is reachable by antibodies, with high confidence; UniProt places it where antibodies can reach, with medium confidence; UniProt predicts a signal peptide or a membrane-spanning region. PROTAC: UniProt records ubiquitination sites on it; a small molecule that binds it is known.
Target class: Family A G protein-coupled receptor; Membrane receptor; Small molecule receptor (family A GPCR); Adenosine receptor; Nucleotide-like receptor (family A GPCR)
Chemical probes: CGS 21680 (high quality), IMARADENANT (high quality), ISTRADEFYLLINE, KW-6356 (high quality), PD080771, PD083169, PD085232, SCH 58261
Safety:
Unwanted effects reported when the protein is acted on. In parentheses: how it was acted on, where the effect was seen, and who reports it.
decreased blood pressure (Bowes et al. (2012): activation, cardiovascular system, central nervous system; Lynch et al. (2017): activation, acute dosing, central nervous system, cardiovascular, blood; Urban et al. (2012): activation, cardiovascular system, nervous system)
arousal (Bowes et al. (2012): inhibition, cardiovascular system, central nervous system; Urban et al. (2012): inhibition, cardiovascular system, nervous system)
coronary vasodilation (Bowes et al. (2012): activation, cardiovascular system, central nervous system; Urban et al. (2012): activation, cardiovascular system, nervous system)
decreased platelet aggregation (Lynch et al. (2017): activation, acute dosing, central nervous system, cardiovascular, blood; Bowes et al. (2012): activation, cardiovascular system, central nervous system)
increased blood pressure (Lynch et al. (2017): inhibition, acute dosing, central nervous system, cardiovascular, blood; Bowes et al. (2012): inhibition, cardiovascular system, central nervous system)
increased heart rate (Bowes et al. (2012): activation, cardiovascular system, central nervous system; Lynch et al. (2017): inhibition, acute dosing and activation, acute dosing, central nervous system, cardiovascular, blood)
increased platelet aggregation (Urban et al. (2012): inhibition, cardiovascular system, nervous system; Lynch et al. (2017): inhibition, acute dosing, central nervous system, cardiovascular, blood)
insomnia (Bowes et al. (2012): inhibition, cardiovascular system, central nervous system; Urban et al. (2012): inhibition, cardiovascular system, nervous system)
sleep induction (Bowes et al. (2012): activation, cardiovascular system, central nervous system; Urban et al. (2012): activation, cardiovascular system, nervous system)
agitation (inhibition; cardiovascular system, nervous system; source: Urban et al. (2012))
antiinflammation (activation; cardiovascular system, nervous system; source: Urban et al. (2012))
cerebral and coronary vasodilation (in microvessels only) (inhibition; cardiovascular system, nervous system; source: Urban et al. (2012))
decreased leukocyte activation (activation; cardiovascular system, central nervous system; source: Bowes et al. (2012))
decreased locomotor activity (activation; cardiovascular system, central nervous system; source: Bowes et al. (2012))
decreased reflex (activation; cardiovascular system, central nervous system; source: Bowes et al. (2012))
hypertension (inhibition; cardiovascular system, nervous system; source: Urban et al. (2012))
increased aggression (inhibition, acute dosing; central nervous system, cardiovascular, blood; source: Lynch et al. (2017))
increased plasma renin activity (activation; cardiovascular system, nervous system; source: Urban et al. (2012))
inhibition of platelet aggregation (activation; cardiovascular system, nervous system; source: Urban et al. (2012))
nervousness (tremors, agitation) (inhibition; cardiovascular system, central nervous system; source: Bowes et al. (2012))
neuroprotective effects (activation; cardiovascular system, nervous system; source: Urban et al. (2012))
potential for stimulation of platelet aggregation (inhibition; cardiovascular system, central nervous system; source: Bowes et al. (2012))
tremors (inhibition; cardiovascular system, nervous system; source: Urban et al. (2012))
adverse events (source: ClinPGx)
adverse events or adverse events (source: ClinPGx)
an adverse event (source: ClinPGx)
anxiety (source: ClinPGx)
Anxiety Disorders (source: ClinPGx)
conflicting evidence reported (source: ClinPGx)
gastrointestinal adverse events (source: ClinPGx)
and 1 more effect
Gene: Protein-coding gene on chromosome 22 (24,417,879 to 24,443,177, forward strand). Ensembl gene ENSG00000128271.
Subcellular location: Cell membrane
Subcellular location (Human Protein Atlas): Plasma membrane; Primary cilium; Vesicles
Pathways (Reactome):
Signal Transduction: Adenosine P1 receptors; G alpha (s) signalling events; NGF-independant TRKA activation
Metabolism of proteins: Surfactant metabolism
Gene Ontology:
Molecular function: calmodulin binding; enzyme binding; G protein-coupled adenosine receptor activity; identical protein binding; lipid binding; protein binding; alpha-actinin binding; G protein-coupled receptor activity; protein-containing complex binding; type 5 metabotropic glutamate receptor binding
Biological process: adenylate cyclase-activating G protein-coupled receptor signaling pathway; response to purine-containing compound; adenylate cyclase-modulating G protein-coupled receptor signaling pathway; apoptotic process; blood circulation; blood coagulation; cell-cell signaling; cellular defense response; central nervous system development; G protein-coupled adenosine receptor signaling pathway; inflammatory response; phagocytosis; sensory perception; synaptic transmission, dopaminergic; astrocyte activation; eating behavior; excitatory postsynaptic potential; G protein-coupled receptor signaling pathway; locomotory behavior; membrane depolarization; negative regulation of cell population proliferation; negative regulation of neuron apoptotic process; negative regulation of vascular permeability; neuron projection morphogenesis; phospholipase C-activating G protein-coupled receptor signaling pathway; and 20 more
Cellular component: plasma membrane; membrane; asymmetric synapse; axolemma; axon; dendrite; glutamatergic synapse; intermediate filament; neuronal cell body; postsynaptic membrane; presynaptic active zone; presynaptic membrane
Genetic constraint (gnomAD): Loss-of-function variants: 11 observed, 21.52 expected, observed/expected ratio (o/e) 0.51, 90% interval 0.32 to 0.85. The upper end of that interval is the gene's LOEUF score, 0.85, which puts it in group 3 of 6, group 1 being the genes least tolerant of losing a copy. Missense variants: 449 observed, 569 expected, observed/expected ratio (o/e) 0.79, 90% interval 0.73 to 0.85. Synonymous variants: 218 observed, 240.99 expected, observed/expected ratio (o/e) 0.9, 90% interval 0.81 to 1.01.
Homologues: Orthologues: chimpanzee ADORA2A (99% identical), rabbit ADORA2A (90% identical), pig ADORA2A (87% identical), guinea pig ADORA2A (87% identical), rat Adora2a (81% identical), mouse Adora2a (81% identical), zebrafish adora2aa (60% identical), tropical clawed frog adora2a (59% identical), Drosophila melanogaster AdoR (33% identical). Paralogues in human: ADORA2B (47% identical), ADORA1 (39% identical), ADORA3 (31% identical).
Diseases named in the same sentence as ADORA2A in open-access papers:
ADORA2A is named in the same sentence as 311 diseases in open-access papers, as found by Europe PMC text mining. Sharing a sentence is not in itself a finding about the gene and the disease. The quoted sentences say what the papers report.
Parkinson disease (112 papers, 2009 to 2025). A progressive degenerative disorder of the central nervous system characterized by loss of dopamine producing neurons in the substantia nigra and the presence of Lewy bodies in the substantia nigra and locus coeruleus. "ADORA2A encodes a member of a G-protein coupled receptor family that functions by increasing cAMP levels using adenosine as its primary agonist and is associated with Parkinson's disease." (PMID 37234859, 2023). "ADORA2A is a strong candidate for validation due to its link to Parkinson disease and functional overlap with CCHS phenotypes." (PMID 37234859, 2023). "Adenosine A2A receptor antagonists can promote the dopamine D2 receptor signaling pathway and show certain anti-Parkinson activity." (PMID 35193486, 2023). "The adenosine A2A receptor is one of the most extensively studied G protein-coupled receptors in human, and has been reported as a promising target for drugs against Parkinson's, cardiovascular and inflammatory diseases." (PMID 35524557, 2022). "The blockade of the adenosine A2A receptor in striatopallidal neurons is known to reduce the postsynaptic effect of dopamine depletion and the motor deficit of Parkinson’s disease (PD)." (PMID 32397307, 2020). "8-Arylethynylxanthine derivatives are potent, selective adenosine A2A receptor antagonists, which represent (potential) therapeutics for Parkinson’s disease, Alzheimer’s dementia, and the immunotherapy of cancer." (PMID 31181839, 2019). "Previous studies have revealed changes of adenosine A2A receptor expression in discrete brain regions of patients dying with Parkinson's disease as well as Parkinson's animal models." (PMID 29163226, 2017). "Building on this background, the current paper investigated SMF by focusing on the adenosine A2A receptor (A2AR) in the PC12 rat adrenal pheochromocytoma cell line that displays metabolic features of Parkinson's disease (PD)." (PMID 21079735, 2010). "Selective adenosine A2A receptor antagonists are currently under clinical trials for treating Parkinson’s disease with encouraging results." (PMID 20190962, 2009). "In this study, a series of novel adenosine A2A receptor antagonists with 1H-pyrazolo [3,4-d]pyrimidin-6-amine core scaffolds was designed and synthesized as potential anti-Parkinson’s disease agents using efficient synthetic methods with three-step short routes." (PMID 35893746, 2022). "Therefore, antagonism of the adenosine A2A receptor has potential to improve mobility for Parkinson’s patients through enhancement of dopaminergic D2 receptor activation." (PMID 33302331, 2020). "Adenosine A2A receptor antagonists are an alternative treatment strategy for Parkinson’s disease." (PMID 29269791, 2017). "In conclusion, the present study indicated that pallidal adenosine A2A receptors play prominent roles in motor modulation under both healthy and parkinsonian states, which further verified that pallidal adenosine A2A receptor is potentially useful in the treatment of Parkinson's disease." (PMID 29163226, 2017). "BackgroundWe evaluated the efficacy and safety of istradefylline, a selective adenosine A2A receptor antagonist administered as adjunctive treatment to levodopa for 12 weeks in a double-blind manner in Parkinson’s disease patients with motor complications in Japan." (PMID 23483627, 2013). "The present adenosine A2A receptor antagonists-induced increase of discharge frequency indicated that adenosine A2A receptor antagonists may contribute to alleviating motor symptoms in Parkinson's disease by normalizing the firing rate of pallidal neurons." (PMID 29163226, 2017). "It was reported that the ADORA2A signaling pathway and the dopamine receptor signaling pathway could competitively regulate microglia-mediated inflammation and improve cognitive dysfunction in patients with Parkinson’s disease by regulating the immune microenvironment." (PMID 35237278, 2022).
Parkinson disease (continued). "Istradefylline (trade name NourianzTM) is an adenosine A2A receptor antagonist approved by the U.S. Food and Drug Administration (FDA) as an add-on treatment to levodopa/carbidopa for adult Parkinson’s disease patients experiencing “off” episodes." (PMID 33302331, 2020). "One of the most extensively studied GPCRs is the human adenosine A2A receptor (A2AR), which has been shown to be a promising drug target for among others Parkinson’s disease, cardiovascular diseases, and inflammatory disorders." (PMID 31127405, 2019). "Notably, A2A-D2 heteromers emerging from the interaction of the adenosine A2A receptor and the dopamine D2 receptor in the striatal neuron plasma membrane opened up new comprehension of the Parkinson’s disease (PD) pathophysiology and of the adverse anti-Parkinson’s drug reaction." (PMID 31109007, 2019). "Adenosine A2A receptor (A2AR) antagonists have emerged as complementary non-dopaminergic drugs to alleviate Parkinson’s disease (PD) symptomatology." (PMID 30405415, 2018). "The adenosine A2A receptor (A2AR) has been studied as a potential therapeutic target in peripheral inflammatory diseases and in brain disorders, such as depression, drug addiction, Alzheimer’s disease, and Parkinson’s disease." (PMID 27539309, 2017). "The aim of this research was to prove the speculation that phenylxanthine (PX) derivatives possess adenosine A2A receptor (A2AR)-blocking properties and to screening and evaluate these PX derivatives as dual A2AR antagonists/MAO-B inhibitors for Parkinson′s disease." (PMID 28629145, 2017).
Anxiety (65 papers, 2006 to 2026). Intense feelings of nervousness, tension, or panic often arise in response to interpersonal stresses. "In humans, Adora2a polymorphisms and sensitivity to caffeine have been linked to anxiety traits, further supporting the idea that interindividual variation in adenosine signaling contributes to psychiatric vulnerability." (PMID 41535618, 2026). "The associations between caffeine-induced anxiety and ADORA2A polymorphisms are particularly noteworthy when considered in the broader context of studies linking ADORA2A to drug-induced anxiety and anxiety disorders." (PMID 40278156, 2025). "Variants in the adenosine A2A receptor gene (ADORA2A) are known to influence sensitivity to CAF central effects (such as anxiety and sleep disturbance) and are now recognized to affect its immunological and endocrine outcomes as well." (PMID 40650030, 2025). "The study also identified two additional SNPs in ADORA2A, rs2298383 and rs4822492, as being associated with caffeine-induced anxiety." (PMID 40278156, 2025). "ADORA2A, the gene encoding A2AR, has several polymorphisms that have been associated with anxiety, depression or cardiovascular disorders." (PMID 38892324, 2024). "A2AR knockout mice also display alterations of anxiety-like behaviors, and ADORA2A polymorphisms are associated with social behavior and exploratory activity, eliciting anxiety-like behavior with the involvement of the anterior cingulate cortex and amygdala." (PMID 36355494, 2022). "The relevance of A2AR in the control of emotional dysfunction is further heralded by the association of polymorphisms of the ADORA2A gene with panic disorders, anxiety and depression." (PMID 36361618, 2022). "Anxiety and sleep disturbance (factors 6 and 7) have been associated with the ADORA2A gene; therefore, future studies should consider these factors when developing a questionnaire capable of discriminating between ADORA2A polymorphisms." (PMID 36014860, 2022). "ADORA2A (rs5751876 C) is thought to increase sensitivity to caffeine as it has been associated with greater caffeine-induced anxiety and alertness and lower caffeine intake in several candidate gene studies." (PMID 34903748, 2021). "Adenosine, its interacting A1 and A2A receptors, and particularly the variant rs5751876 in the A2A gene ADORA2A have been shown to modulate anxiety, arousal, and sleep." (PMID 33235193, 2020). "CYP1A2 is responsible for the majority of the metabolism of caffeine, and ADORA2A has been linked to caffeine-induced anxiety." (PMID 30248915, 2018). "The result showed significant association between caffeine-induced anxiety and specific ADORA2A polymorphism (rs5751876, rs2298383, rs4822493) and DRD2 polymorphism (rs1110976)." (PMID 31435520, 2018). "In support of adenosine being anxiogenic, an adenosine A2A receptor antagonist reduced anxiety and stress in rodents that was caused by maternal separation or chronic unpredictable stress." (PMID 28335379, 2017). "Polymorphisms of ADORA2A have been previously implicated in caffeine-induced anxiety as well as habitual caffeine intake." (PMID 21490707, 2011). "Moreover, polymorphisms in the Adora2a gene are classified as anxiogenic and are associated with increased glutamatergic transmission in anxiety and depressive disorders." (PMID 41535618, 2026). "Physical performance may be differentially affected by caffeine depending on CYP1A2 genotype, whereas anxiety and sleep disturbance have been associated with the ADORA2A gene." (PMID 36014860, 2022). "These two findings may be related because we find that the ADORA2A gene, a dopaminergic gene, is associated with both feelings of energy and anxiety." (PMID 33525438, 2021). "In contrast, polymorphisms affecting ADORA2A could lead to an individual to experience greater sleep disturbance, impacting athletes that compete in the evening, or increased anxiety resulting in poor competition performance." (PMID 33671206, 2021).